HNF1A (HNF1 homeobox A)
Diseases named in the same sentence as HNF1A in open-access papers (continued):
Sharing a sentence is not in itself a finding about the gene and the disease.
diabetes (continued). "Of the adult diabetes patients with no molecular diagnosis, seven had complete testing of HNF1A and HNF4A including multiplex ligation‐dependent probe amplification (MLPA) for deletions and duplications." (PMID 27330718, 2016). "HNF1A-MODY is characterized by progressive hyperglycemia, with the onset of diabetes in youth." (PMID 27807544, 2016). "Four of the patients with no molecular diagnosis were only tested for the mitochondrial mutation, as their phenotype was not thought to be compatible with HNF1A or HNF4A diabetes." (PMID 27330718, 2016). "We previously postulated that cystatin C level might also be a biomarker for HNF1A-MODY, a monogenic form of diabetes, as concomitant kidney phenotypes were described in this form of disease." (PMID 26347889, 2015). "Other studies have identified high-sensitivityC-reactive protein (hsCRP), a known HNF1A target gene to be reduced in serum levels of subjects with HNF1A-MODY, compared to other forms of diabetes such as type 1 diabetes, type 2 diabetes, HNF4A-MODY, and glucokinase-MODY." (PMID 23803251, 2013). "Consideration of genetic testing for HNF4A should therefore be considered in patients with clinical features suggestive of HNF1A monogenic diabetes but negative genotyping and those with a positive family history of macrosomia or neonatal hypoglycaemia." (PMID 23766565, 2013). "We recruited 37 participants with HNF1A-MODY diabetes and compared levels of sCD36 with BMI-matched participants with type 2 diabetes mellitus and normoglycaemic HNF1A-MODY negative family controls." (PMID 24069322, 2013). "Unlike, HNF1A and HNF4A monogenic diabetes, pancreatic atrophy is common in those with HNF1B mutations, therefore carriers do not display the same sensitivity to SU therapy and often require insulin therapy." (PMID 23766565, 2013). "Concordant with recent publications, HNF1A-MODY subjects had substantially lower hsCRP levels compared with other diabetes subtypes, but also to non-diabetic individuals (p < 0.0001, for all pairwise comparisons)." (PMID 22350134, 2013). "Unlike typical HNF1A variants in MODY3, the diabetes phenotype that emerged in this private polymorphism was non-MODY type 2 diabetes, although the S319 allele was associated with accelerated onset of type 2 diabetes in a gene-dosage manner in this population." (PMID 20716378, 2010). "Five children (8%) had pathogenic variants that do not cause syndromic diabetes (GCK [n = 2], HNF1A [n = 1], INS [n = 1], and the PTF1A enhancer [n = 1]); thus, these additional features are likely to be coincidental and unrelated to the monogenic diabetes diagnosis." (PMID 40746173, 2026). "Although no convincing Hnf1α gene variant-induced abnormal endocytosis has been identified in humans, individuals with HNF1α mutations exhibit low molecular weight proteinuria compared to individuals with non-MODY HNF1A diabetes." (PMID 40149950, 2025). "From the results of lipid metabolism, we found that GCK‐MODY patients have lower TG than HNF1A‐MODY patients in the follow‐up period, and comparison with type 2 diabetes patients also showed a tendency toward lower TG in GCK‐MODY in the all‐family‐members subgroup (with longer diabetes duration)." (PMID 37226652, 2023). ",4HNF1A/HNF4A-MODY (HNF1A-MODY, MIM: 600495; HNF4A-MODY, MIM: 125850) are better treated with oral sulphonylureas whereas GCK-MODY (MIM: 125851) does not need treatment and is not at high risk of diabetes-related complications." (PMID 36257325, 2022). "Similarly, Hnf1a mouse models with heterozygous KO present without developing diabetes, whereas a homozygous KO impairs β-cell function by reducing the insulin secretion." (PMID 34079523, 2021). "However, in our study GCK and HNF1A-MODY patients showed comparable levels of fasting glucose, and none of them had a level of fasting glucose > 8.33 mmol/l, except for the HNF1A-MODY patient who presented DKA at diabetes onset." (PMID 34496959, 2021).
diabetes (continued). "The age at diagnosis of diabetes was higher in HNF4α- and HNF1β-MODY probands than in the other MODY types, including MODY X. MODY X probands exhibited higher fasting glucose levels and glucose levels at 60 min during an OGTT compared with those of GCK-, HNF1α-, and HNF4α-MODY probands." (PMID 34746319, 2021). "Plasma 1,5-AG and serum hsCRP do not discriminate sufficiently HNF1A MODY from common diabetes types, but could be potentially useful in prioritizing Sanger sequencing of HNF1A gene." (PMID 30778899, 2019). "Our study suggests that, in individuals with HNF1A/HNF4A-MODY with a longer duration of diabetes (>11 years) at time of genetic test, rather than ceasing current treatment, a sulfonylurea should be added to existing therapy, particularly in those who are overweight or obese and have a high HbA1c." (PMID 30229274, 2018). "The lack of optimal glycaemic control in our study may have resulted from clinical inertia or limited experience among local clinicians in managing HNF1A/HNF4A-MODY and previous advice advocating a trial of sulfonylureas even in those with longstanding diabetes." (PMID 30229274, 2018). "Post-hoc analysis revealed significant differences in mean glucose to creatinine ratio change between type 2 diabetes and each monogenic diabetes in response to dapagliflozin (p = 0.02, p = 0.003 for HNF1-A and GCK MODY, respectively), but not between the two MODY forms (p = 0.7231)." (PMID 28593615, 2017). "However, in MODY genes such as HNF1A and HNF4A, not all missense mutations increase the risk for diabetes and, therefore, it is challenging to ascribe pathogenicity to a novel missense mutation based on predictions made by bioinformatics tools." (PMID 29207974, 2017). "HNF4A-MODY subjects have similar progressive diabetic phenotype to HNF1A-MODY subjects, except that HNF4A mutations are associated with macrosomia, transient and persistent neonatal hypoglycaemia, later age of diabetes onset and the absence of low renal threshold." (PMID 23803251, 2013). "In contrast to type 1 diabetes mellitus patients who have a rapid disease onset, HNF1A-MODY carriers represent an interesting and important study group for the study of beta cell apoptosis during disease progression as carriers will ultimately develop diabetes." (PMID 22808921, 2012). "Furthermore, in a study involving 922 families referred for MODY testing, spontaneous de novo mutations affecting the GCK, HNF1A, or HNF4A genes were reported in 11 of 150 individuals who did not have autosomal dominant inheritance of diabetes or a multigenerational family history of hyperglycemia." (PMID 39902162, 2024). "In the present study, we show that 16 of 623 (2.6%) Norwegian children with antibody-negative diabetes (representing 0.3% of the NCDR) carry variants leading to impaired protein function of HNF1A, with phenotypic and functional investigations supporting HNF1A-MODY." (PMID 37798422, 2023). "However, HNF1α+/− mice do not develop diabetes and HNF1α−/− mice show growth retardation, impaired insulin release, and aerobic glucose metabolism, but unlike MODY3 patients suffer from other renal and kidney complications due to the pleiotropic effect of complete loss of HNF1α." (PMID 35235779, 2022). "And although individuals with HNF1A-MODY are more sensitive to sulfonylureas than those with type 2 diabetes, their beta cell response to sulfonylureas is similar to that in control individuals without diabetes, rendering it unlikely that the MODY variant directly affects sulfonylurea sensitivity." (PMID 34951657, 2022). "Therefore, it is not clear whether the ED found in HNF1A-MODY patients could be due to the diabetes complications or is rather genetic consequence." (PMID 31739614, 2019).
diabetes (continued). "However, only 58% of individuals with HNF1A/HNF4A-MODY were on diet or sulfonylurea alone at 2 years and, overall, just 36% of individuals with HNF1A/HNF4A-MODY who changed treatment achieved the good glycaemic control (≤58 mmol/mol [≤7.5%]) needed to avoid diabetes complications." (PMID 30229274, 2018). "Furthermore the study aimed at determining whether mutations in KCNJ11, ABCC8, HNF1A, HNF4A or INS are common in AAB negative diabetes." (PMID 20863361, 2010). "Outside of our clinically referred to cohort, we found that most individuals with HNF1A- and HNF4A-MODY did not develop diabetes even by 50 years of age (∼50% and ∼80% in Geisinger and UK Biobank, respectively)." (PMID 36257325, 2022). "Due to the family history of diabetes (mother and grandmother on treatment with oral hypoglycemic drugs), genetic tests for the most common forms of MODY were performed (GCK-, HNF1A-, and HNF4A- MODY) and found negative." (PMID 36294752, 2022). "A subsequent multicenter study confirmed its satisfactory performance as an HNF1A MODY biomarker, while recently published results suggest its inferior utility among patients with antibody-negative diabetes." (PMID 30778899, 2019). "When multivariate analysis was performed accounting for age and duration of diabetes status the levels of sCD36 remain significantly different between HNF1A-MODY participants and normoglycaemic HNF1A-MODY negative controls." (PMID 24069322, 2013). "Levels of sCD36 in HNF1A-MODY did not correlate with age, duration of diabetes or glycaemic control as determined using HbA1c." (PMID 24069322, 2013). "In conclusion, sCD36 is significantly lower in lean participants with HNF1A-MODY diabetes when compared to weight-matched normoglycaemic familial HNF1A-MODY negative controls and to lean participants with type 2 diabetes mellitus." (PMID 24069322, 2013). "Insulin secretory defects have been observed in carriers of HNF1A-MODY and GCK-MODY with and without diabetes." (PMID 22808921, 2012). "Patients with HNF1A-MD often respond well to low-dose sulfonylureas, whereas GCK-hyperglycemia is typically mild and may not even meet formal diabetes criteria." (PMID 41409604, 2025). "Altogether, this suggests that the carriers might have a combination of type 2 diabetes and HNF1A-MODY, which is not uncommon, or a phenotype representing a possible continuum of diabetes sub-phenotypes from MODY to type 2 diabetes." (PMID 32910913, 2020). "However, because of the lack of standard antibody testing in those with diabetes, a proportion of individuals with MODY subtypes (such as HNF1A/HNF4A-MODY) may be misdiagnosed as having type 1 diabetes." (PMID 37897565, 2023). "Combined with the result that GCK‐MODY probands were about 0.87 years younger at recruitment compared to those with HNF1A‐MODY, we speculate that there may be no actual difference in age at diagnosis of diabetes between patients with GCK‐MODY and those with HNF1A‐MODY." (PMID 37226652, 2023). "Moreover, HDL cholesterol values measured in individuals with likely monogenic diabetes may be useful in screening for GCK-MODY and its differentiation from DM1 and HNF1A-MODY, regardless of treatment or metabolic control." (PMID 28663157, 2017).
MODY (227 papers, 2008 to 2026). "Similar to MC4R, HNF1A harbors variants that cause maturity-onset diabetes of the young (MODY25) as well as rare and common variants associated with adult-onset T2D26." (PMID 37292813, 2023). "HNF1A gene underlies the development of one of the most common forms of monogenic maturity-onset diabetes of the young (MODY), known as MODY3, a type of autosomal dominant diabetes with early onset." (PMID 37509590, 2023). "Previous studies have established that HNF1A mutations are associated with hepatocellular adenomas and maturity-onset diabetes of the young type 3 (MODY3)." (PMID 35327967, 2022). "A study of an Italian family linked the SNP in the hepatocyte nuclear factor 1 alpha (HNF-1α) gene regulatory region with the Maturity-onset diabetes of the young 3 (MODY3) as a result of disruption of the transcription factor HNF-4α binding site." (PMID 33371430, 2020). "Most cases are caused by mutations in GCK [glucokinase gene] (GCK MODY [maturity onset diabetes of the young]) or HNF1A [hepatocyte nuclear factor 1-alpha gene] (HNF1A MODY)." (PMID 31576961, 2020). "HNF1A mutations cause maturity-onset diabetes of the young (MODY) type 3 and rare variants in this gene increase type 2 diabetes risk." (PMID 32847508, 2020). "This is consistent with reports showing that the loss-of-function mutations in the HNF1α-encoding gene associated with maturity-onset diabetes of the young (MODY) lead to a significant reduction in circulating CRP concentrations." (PMID 29330688, 2018). "The most common form of maturity-onset diabetes of the young (MODY) is caused by mutations in the hepatocyte nuclear factor 1A (HNF1A) gene." (PMID 26942212, 2016). "A number of mutations of HNF1A gene were associated with maturity-onset diabetes of the young (MODY), an early onset form of type 2 diabetes." (PMID 27460564, 2016). "In humans, Hnf1a mutations are the most common cause of maturity-onset diabetes of the young (MODY)." (PMID 26555648, 2015). "Maturity-onset diabetes of the young type 3 (MODY3) is caused by heterozygous mutation in the HNF1A gene." (PMID 22672869, 2012). "Other, less frequent variants were related to HNF1A-maturity onset of diabetes of the young, MODY, (n = 7, 0.18%); HFE-related haemochromatosis (n = 2, 0.05%); ACVRL1-hereditary haemorrhagic telangiectasia (n = 2, 0.05%); and ATP7B–Wilson disease (n = 1, 0.03%)." (PMID 40332002, 2025). "Pathogenic coding variants in HNF1A cause maturity onset diabetes of the young (MODY)." (PMID 41279449, 2025). "Among these, maturity-onset diabetes of the young type 3 (MODY 3) caused by mutations in the hepatocyte nuclear factor 1-alpha (HNF1A) gene is the most frequent form, accounting for 30-70% of genetically confirmed cases depending on population and diagnostic strategies." (PMID 41367451, 2025). "Furthermore, heterozygous germline mutations in HNF1A are associated with an autosomal dominant condition, maturity onset diabetes of the young type 3 (MODY3)." (PMID 37835484, 2023). "Variant rs1169305 (HNF1A) is assigned to maturity-onset diabetes of young type 3 (MODY3) and might also result in hepatic adenomas (NCBI ClinVar)." (PMID 32708070, 2020). "Mutations of the HNF1A gene cause maturity onset diabetes of the young (MODY)." (PMID 25987348, 2015). "We compared these to 7645 non-diabetic control participants, 4773 participants with type 2 diabetes and 601 participants with HNF1A-MODY and assessed associations between PGS and glycaemic measures." (PMID 41848901, 2026). "Standard genetic testing for MODY often focuses on sequencing, which can lead to the misdiagnosis of cases caused by HNF1A copy number variants (CNVs)." (PMID 41778156, 2026). "Large HNF1A deletions, undetectable by standard sequencing, can cause MODY and necessitate copy number variant (CNV) analysis." (PMID 41778156, 2026).
MODY (continued). "It is well known that patients with HNF1A-MODY have the same risk of developing microvascular and macrovascular complications as those with type 1 diabetes and type 2 diabetes, especially in cases of poor glycemic control." (PMID 39903441, 2025). "The first-reported MODY-causing variants in our high penetrance control HNF1A are all rare (allele frequency < 1x10-5 in gnomAD v2.1.1)." (PMID 40779032, 2025). "Thirteen MODY subtypes have been identified so far, with HNF1A, HNF4A, and GCK mutations accounting for the majority of cases." (PMID 40777711, 2025). "Future studies should gather further empirical evidence showing that MODY is caused by disrupted TF cooperativity or positive feedback (beyond HNF1A and HNF4A)." (PMID 41356216, 2025). "Several genetic subtypes of MODY exist, with the most common being mutations in HNF1A, HNF4A, and GCK genes." (PMID 40777711, 2025). "Genetic analysis later confirmed an HNF1A mutation, establishing MODY 3 and allowing more appropriate treatment and counselling." (PMID 41367451, 2025). "Identifying mutations in Hnf1α gene is important for diagnosing MODY and understanding its mechanisms, which can guide the development of targeted molecular therapies for precision medicine." (PMID 40149950, 2025). "Among the confirmed MODY genes, mutations in HNF1A, GCK, and HNF4A remain the most common, collectively accounting for approximately 90% of all genetically confirmed cases." (PMID 41367630, 2025). "Many MODY-associated TF genes show incomplete penetrance, e.g., HNF1A, HNF1B, HNF4A, NEUROD1, PDX1, and RFX6." (PMID 41356216, 2025). "Novel MODY genes will perhaps be more like this and less likely the most common causes of MODY such as HNF1A where you expect to see large pedigree with high cosegregation." (PMID 40819284, 2025). "Conversely to GCK-MODY, in the most frequently occurring HNF1A-MODY (MODY3) variant, pregnancy outcomes are largely dictated by the glycemic regulation of the mother instead of the fetal mutation status." (PMID 40649834, 2025). "Maturity-onset diabetes of the young (MODY), particularly due to HNF1A variants, is usually treated with sulfonylureas or insulin." (PMID 41262822, 2025). "Taken together with the affinity measurements and transactivation activities of HNF-1A, our data strongly suggest that an impairment of HNF-1A–mediated gene transcription is causative for MODY in these patient groups." (PMID 38855865, 2024). "There are few reports of the coinheritance of glucokinase (GCK) and hepatocyte nuclear factor 1 alpha gene (HNF1A) variants underlying MODY in patients." (PMID 39089324, 2024). "Maturity-onset diabetes of the young (MODY), caused by mutations in the HNF1A gene, is also a rare disorder; all types of MODY account for 1–2% of adult diabetic cases." (PMID 38311659, 2024). "The P2-HNF4A promoter presents an important link between MODY-associated genes, as it harbors transcription factor binding sites for HNF-1A, HNF-1B, PDX1, and HNF-6." (PMID 38855865, 2024). "Genetic variants in HNF4A and HNF1A are known to be causal for MODY (through a beta cell defect) and have also been robustly associated with T2D risk, implicating a clear role in regulating pancreatic beta cell function." (PMID 38909044, 2024). "Variants in glucokinase (GCK) and hepatocyte nuclear factor (HNF1A/4A) genes are the most common causes of MODY." (PMID 39420902, 2024). "Herein, we describe a case involving combinations of monoallelic GCK and HNF1A variants associated with MODY." (PMID 39089324, 2024). "Considering these expression patterns and the age of onset for MODY, we believe that an impaired HNF-1A–mediated gene transcription is likely the disease-causing factor, even though an involvement of HNF-1B in disease predisposition or progression is possible." (PMID 38855865, 2024). "Maturity-onset diabetes of the young (MODY) is an inherited autosomal dominant condition, most commonly caused by mutations in HNF1A (MODY 3) and GCK (MODY 2)." (PMID 37159865, 2023).